VDR (vitamin D receptor)
Diseases named in the same sentence as VDR in open-access papers (continued):
Sharing a sentence is not in itself a finding about the gene and the disease.
uterine fibroids (8 papers, 2017 to 2025). "Some studies have recently shown that vit D deficiency is an important risk factor for uterine fibroids and uterine fibroids express lower levels of vit D receptor (VDR) compared with myometrium." (PMID 31363390, 2019). "For genotyping the fok1 polymorphism of the vitamin D receptor, real-time polymerase chain reaction was performed on blood samples of uterine leiomyoma (n=27) and control (n=33) groups." (PMID 29391329, 2018). "Evidence shows that the expression of VDR in most cells could be an important cellular biomarker associated with the etiology of uterine leiomyomas." (PMID 33952298, 2021). "VDR polymorphisms have not only been associated with uterine leiomyomas." (PMID 29391329, 2018). "Monitoring VDR gene polymorphisms and its molecular associations could give a route for the prognosis of uterine leiomyomas, and further, identify potential targets for the development of novel treatments as personlised medicine." (PMID 29391329, 2018). "Transcriptomic profiling of uterine leiomyomas has revealed increased VDR mRNA expression in specific tumor regions, suggesting localized adaptive responses within hyperplastic lesions." (PMID 41394244, 2025). "The reduction in VDR expression would be a factor reducing the antiproliferative activity of vitamin D, thereby contributing to the pathogenesis of uterine leiomyomas." (PMID 33952298, 2021). "Some studies show that vitamin D receptor (VDR) expression is correlated with the etiology of uterine leiomyomas." (PMID 33952298, 2021). "A protective effect of vitamin D on uterine leiomyoma has been suggested and is biologically plausible as the vitamin D receptor (VDR) has been shown to be expressed in both myometrial and leiomyoma tissues." (PMID 28930160, 2017). "This concept is further supported by studies in uterine leiomyomas, where VDR expression was found to be significantly lower in neoplastic tissue compared to normal myometrium, suggesting that reduced VDR expression may facilitate aberrant growth." (PMID 41394244, 2025). "Lower VDR expression may reducing the antiproliferative activity of vitamin D, thereby contributing to the formation of uterine leiomyomas." (PMID 36014877, 2022). "However, further studies are needed to assess the real importance of VDR expression in the etiopathogenesis of uterine leiomyomas." (PMID 33952298, 2021). "Studies demonstrating the identification of VDR expression in most cells and the ability of some cells to produce active forms of vitamin D have suggesting an influence of this vitamin on the pathogenesis of uterine fibroids." (PMID 33952298, 2021). "The study results showed a reduced expression of VDR in the uterine leiomyoma compared to nonneoplastic myometrial tissue." (PMID 36014877, 2022). "There was no statistical correlation of expression of vitamin D receptor expression in uterine leiomyoma tissue with age, parity, tumor size, uterine volume or nutritional status." (PMID 33952298, 2021). "In this study, we evaluated the expression of the biomarker VDR in human uterine leiomyoma tissue and compared it that in nonneoplastic myometrial tissue." (PMID 33952298, 2021). "In conclusion, we observed significantly reduced VDR expression in human uterine leiomyomas compared with in nonneoplastic myometrial samples." (PMID 33952298, 2021). "The mean percentage of nuclei expressing VDR was significantly lower in the uterine leiomyoma than in nonneoplastic myometrial tissue." (PMID 33952298, 2021). "This study aimed to assess the expression of VDR in uterine leiomyoma and nonneoplastic myometrial tissue." (PMID 33952298, 2021). "In that research, VDR was not studied in women without uterine fibroids." (PMID 36014877, 2022). "Thus, the present study aimed to evaluate VDR expression in uterine leiomyomas and in adjacent nonneoplastic myometrial tissue." (PMID 33952298, 2021).
basal cell carcinoma (7 papers, 2008 to 2024). A carcinoma involving the basal cells. "Human trichofolliculomas (hair follicle tumours) are characterized by high nuclear β-catenin and VDR, whereas infiltrative basal cell carcinomas (BCCs) have high β-catenin and low VDR levels." (PMID 18213391, 2008). "Potential effects of 1,25(OH)2D3 and its receptor (VDR) on the expression of IL-33 and ST2 were tested in cultured keratinocytes, melanocytes, fibroblasts, and basal cell carcinoma cells." (PMID 34884710, 2021). "Conversely, in the absence of VDR differentiation of ectopic follicles is inhibited and the tumours that develop in response to β−catenin are undifferentiated basal cell carcinomas." (PMID 18213391, 2008).
Behcet disease (7 papers, 2016 to 2023). A chronic, relapsing, multisystemic vasculitis characterized by mucocutaneous lesions, as well as articular, vascular, ocular and central nervous system manifestations. "The possible VDR SNP involvement in Behcet’s disease susceptibility needs to be investigated in larger cohorts of various ethnicities, as the results of the meta-analysis we summarized were based on a relatively small sample size of cases and controls." (PMID 37508347, 2023). "In this study we aimed to demonstrate any association or susceptibility between VDR gene polymorphisms and Behçet's disease group consisting of patients with neuro-Behçet's and Behçet's disease." (PMID 27688524, 2016). "There are only three publications exploring the VDR polymorphisms in Behçet's disease." (PMID 27688524, 2016). "Epigenetic changes of the VDR gene have also been investigated in Behcet’s disease (BD), a chronic recurrent multisystem inflammatory condition caused by several pro-inflammatory cytokines regulated by 1,25(OH)2D3." (PMID 38203278, 2023). "Although studies investigating VDR SNPs in Behçet's disease are very few, many studies focusing on Turkish population were performed in various diseases." (PMID 27688524, 2016). "Recently polymorphisms in Vitamin D receptor (VDR) and 7-dehydrocholesterol reductase (DHCR7) genes have been associated with Behçet’s disease." (PMID 27716192, 2016).
chronic hepatitis B (7 papers, 2013 to 2024). "VDR SNPs have been linked to carcinogenesis in a variety of organs, including the breast, uterus, skin, colon and rectum, and kidneys, and have been studied in chronic liver diseases, such as chronic hepatitis B virus infections." (PMID 35996514, 2022). "Genotype frequencies of DHCR7, CYP27B1, CYP2R1, GC and VDR in HBeAg-positive chronic hepatitis B patients treated with PegIFN for 48 weeks." (PMID 28296915, 2017).
colorectal tumor (7 papers, 2009 to 2023). "In this context, a high-level expression of the VDR has been observed in an early colorectal tumor progression, but a loss of the VDR expression was reported during the tumor dedifferentiation." (PMID 31231490, 2019). "The discrepancies with the risk association of the VDR polymorphisms and colorectal tumors in various investigations could be due to the different genetic background of cancers where haplotype clusters might have more relevance rather than individual genotype." (PMID 27309378, 2016). "were associated with prevention/protection against large intestine neoplasms, including GUCA2A, CDX2, VDR, VEFGA, GSTM1, HPGD, and PPARG." (PMID 37296943, 2023). "Furthermore, TTI-101 treatment also led to the upregulation of important genes such as GUCA2A, CDX2, VDR, GSTM1, HPGD, and PPARG that have been shown by others to be associated with the prevention of large intestine neoplasms." (PMID 37296943, 2023). "Finally, the benefits from vitamin D supplementation for the prevention of colorectal neoplasms may vary according to genetic variation in the vitamin D-related genes (e.g., vitamin D receptor (VDR))." (PMID 31434255, 2019).
diabetic neuropathy (7 papers, 2018 to 2025). A chronic, pathological complication associated with diabetes mellitus, where nerve damages are incurred due to diabetic microvascular injury involving small blood vessels that supply these nerves, resulting in peripheral and/or autonomic nerve dysfunction. "In vivo, an increase in vitamin D receptor was observed in neurons of diabetic rats, which indicated that the vitamin D receptor signaling system could be a potential therapeutic target for diabetic neuropathy." (PMID 35025861, 2022). "We aimed to analyse Sirtuin 1 (SIRT1) and Vitamin D receptor (VDR) expression levels in the peripheral blood of patients with type 2 diabetes (T2D), characterized for the presence of diabetic neuropathy (DN), and to evaluate possible genetic factors that could influence the VDR expression levels." (PMID 39976627, 2025). "In addition, polymorphisms in vitamin D receptor (VDR) gene were described in association with type 1 and 2 diabetes mellitus, although there are no data about its correlation with diabetic neuropathy susceptibility." (PMID 33329405, 2020).
esophageal adenocarcinoma (7 papers, 2006 to 2024). A malignant tumor with glandular differentiation arising predominantly from Barrett mucosa in the lower third of the esophagus. "This study aims to expand on this limited evidence, to investigate the association between VDR expression and prognosis in oesophageal adenocarcinoma patients who have undergone neoadjuvant chemotherapy and surgical resection." (PMID 30344947, 2018). "This study has several strengths, including being the first study to identify VDR as potential biomarker to predict outcomes in oesophageal adenocarcinoma, and only the second study to investigate this association." (PMID 30344947, 2018). "Our study provides some evidence that VDR is associated with oesophageal adenocarcinoma outcomes, and therefore indirect evidence of a biological role for vitamin D." (PMID 30344947, 2018). "This study aims to evaluate the association between VDR expression and prognosis in oesophageal adenocarcinoma patients." (PMID 30344947, 2018). "This study is the first to demonstrate a significant, dose-response, association between higher VDR expression and improved survival in patients with oesophageal adenocarcinoma." (PMID 30344947, 2018). "To date, only one study has investigated the association between VDR expression and oesophageal adenocarcinoma outcomes in 116 patients." (PMID 30344947, 2018). "Evidence from our study demonstrates for the first time that any association between circulating vitamin D levels and oesophageal adenocarcinoma outcomes, mediated by VDR expression, may be biologically plausible." (PMID 30344947, 2018). "This study is the first to demonstrate that patients with higher VDR expression in oesophageal adenocarcinoma have a more favourable prognosis." (PMID 30344947, 2018). "Although there is limited research looking at the impact of high VDR expression in oesophageal adenocarcinoma outcomes, there are multiple other clinical studies which look at the impact of high VDR expression on survival in patients with other cancer sites." (PMID 30344947, 2018). "To date, there has been little research investigating VDR expression and oesophageal adenocarcinoma outcomes." (PMID 30344947, 2018). "Further work is needed to validate these findings, and to define the role of VDR in the aetiology, progression and management of oesophageal adenocarcinoma." (PMID 30344947, 2018). "Similar findings were observed in a small study which assessed VDR expression in tumour, adjacent normal and Barrett's mucosa, from five oesophageal adenocarcinoma resection specimens." (PMID 30344947, 2018). "In conclusion, in this Northern Irish population, patients with higher VDR expression in oesophageal adenocarcinoma have a more favourable prognosis." (PMID 30344947, 2018). "However, further work is needed to validate these findings and define the role of VDR in the aetiology, management and progression of oesophageal adenocarcinoma." (PMID 30344947, 2018). "However, several published papers have reported differences in VDR expression when comparing native, pre-malignant and oesophageal adenocarcinoma tissue in cross-sectional analyses from different patients." (PMID 30344947, 2018). "The implications of VDR expression on further progression of columnar epithelium to oesophageal adenocarcinoma, and prognosis after adenocarcinoma development remains unclear." (PMID 30344947, 2018). "However, further studies that incorporate assessment of serum 25-hydroxyvitamin D status in addition to tumour VDR expression in patients with oesophageal adenocarcinoma are required to corroborate this hypothesis." (PMID 30344947, 2018). "In contrast to the findings that VDR gene polymorphisms seem not related to the esophageal adenocarcinoma (EAC) risk development, we previously showed a significantly increased risk of esophageal squamous cell carcinoma associated with VDR rs2107301 T>C polymorphism among patients who were drinking." (PMID 28489590, 2017).
esophageal adenocarcinoma (continued). "We recently found that bile salt receptors VDR and TGR5 were highly expressed in esophageal adenocarcinoma (EAC) and precancerous lesions." (PMID 28212604, 2017). "In cell cultures, the expression of FXR was high in Barrett's esophagus-derived cells and almost undetectable in adenocarcinoma-derived cells, whereas VDR expression in these cell lines was not significantly different." (PMID 17054793, 2006). "However, the biological functions of VDR in oesophageal adenocarcinoma are not clear." (PMID 37561808, 2023).
gynecological cancers (7 papers, 2017 to 2024). "The vitamin D receptor (VDR) is upregulated in all gynecological cancers, indicating its influence on cancer etiology." (PMID 29113037, 2017). "In the recent years, the vitamin D receptor has gained attention in gynecological cancers." (PMID 29113037, 2017). "The interaction of VDR with the RXR implies that also the RXR may have a modulating effect on gynecological cancers." (PMID 29113037, 2017). "The relationship between vitamin D/VDR and gynecological cancers should be the focus of future studies which could lead to a better understanding of the molecular pathways." (PMID 29113037, 2017). "Several studies have highlighted the potential of VDR as a prognostic and therapeutic target for CESC, a prevalent gynecological cancer." (PMID 39268267, 2024).
head and neck squamous cell carcinoma (7 papers, 2011 to 2025). A squamous cell carcinoma that arises from any of the following anatomic sites: lip and oral cavity, nasal cavity, paranasal sinuses, pharynx, larynx, and salivary glands. "Consistent with our findings, previous research has demonstrated that VDR is expressed in head and neck squamous cell carcinoma (HNSCC) tumors, and that adding 1,25(OH)2D3 to chemotherapy can reduce tumor growth and cell migration." (PMID 40724881, 2025). "The biologically active form of D3(1,25-(OH)2D3)binds to the VDR and arrests cells in the G0/G1 phase, thereby inhibiting proliferation and inducing differentiation in various malignancies, such as cell lines of head and neck squamous cell carcinoma (SCCHN)." (PMID 41246358, 2025).
Hepatitis (7 papers, 2013 to 2025). Inflammation of the liver. "VDR expression negatively correlates with the degree of hepatocyte injury in hepatitis." (PMID 40547375, 2025). "Consistent with the effects in vivo with hepatocyte VDR deletion, genes involved in liver proliferation, hepatitis, liver hyperplasia/hyperproliferation, and liver necrosis/cell death pathways were overrepresented in genes that were significantly altered by vitamin D treatment." (PMID 38963813, 2024). "The frequency of VDR Taq T/t in carriers with hepatitis flare(s) was significantly higher than those without, which suggests adverse clinical outcomes in HBV carriers." (PMID 27785252, 2013). "However, neither VDR BsmI, ApaI, nor TaqI were associated with HCC in Taiwanese with hepatitis B carriers." (PMID 35996514, 2022).
ischemic stroke (7 papers, 2020 to 2024). A stroke disorder caused by obstruction of blood flow to the brain, due to thrombotic (local blood clot formation) or embolic (due to a blood clot or other material traveling from another site) event. "Genetic variants in VDR were also found to be associated with susceptibility to ischemic stroke." (PMID 36890539, 2023). "Following ischemic stroke, microglia/macrophage VDR-CKO mice exhibit an enhanced M1 phenotype in microglia/macrophages, with substantial secretion of TNF-α and IFN-γ." (PMID 39649720, 2024). "Conversely, even short-term androgen excess with lacking VDR signaling may lead to unfavorable outcomes of ischemic stroke, highlighting the complex interplay between sex steroids and vitamin D in terms of cerebrovascular diseases." (PMID 37764653, 2023). "Remarkably, defective VDR signaling in microglia/macrophages resulted in pronounced upregulation of chemokines after acute ischemic stroke, including CXCL10 and CCL2, together with aggravated disruption of the BBB and infiltration of peripheral T cells and monocytes/macrophages." (PMID 36890539, 2023). "Our findings suggest that the polymorphisms of VitD metabolic pathway genes VDR and CYP27B1 may be associated with PSD in patients with ischemic stroke." (PMID 37404714, 2023). "Moreover, the vitamin D receptor was demonstrated to mediate the protective effect of vitamin D-induced expression of occludin, claudin-5 and zonula occludens in ischemic stroke." (PMID 31930458, 2020). "In sum, the absence of VDR in microglia/macrophages significantly heightened the ischemia-elicited inflammatory milieu in the acute phase of ischemic stroke." (PMID 36890539, 2023).
leiomyoma (7 papers, 2017 to 2025). A well-circumscribed benign smooth muscle neoplasm characterized by the presence of spindle cells with cigar-shaped nuclei, interlacing fascicles, and a whorled pattern. "In vitro studies documented that TGFβ-1 treatment and vitamin D3 have opposite effects on α-SMA, TGFβR2 and VDR expression on dermal fibroblast and leiomyoma cell cultures." (PMID 37606484, 2023). "The vitamin D/VDR complex regulates the expression of genes and is involved in the pathogenesis of fibroids." (PMID 36014877, 2022). "The results of other studies also indicated VDR expression in unchanged tissue in women with fibroids." (PMID 36014877, 2022). "It was revealed that the expression of VDR was significantly lower in the myometrium in the peripheries of fibroids than in the uterine muscle in the control group." (PMID 36014877, 2022). "Using immunohistochemical methods, this study was designed to assess the VDR which leads to the pathogenesis of fibroids." (PMID 36014877, 2022). "Samples of myoma and myometrial tissue from different sites in five women who underwent hysterectomy were evaluated, and high VDR expression was observed in the central part of the leiomyoma samples compared to the myometrial samples." (PMID 33952298, 2021). "The results of the present study demonstrate reduced VDR expression in leiomyoma tissue compared with myometrial tissue,suggesting an association with the pathogenesis and development of human uterine leiomyomatosis." (PMID 33952298, 2021). "The percentage of cells with nuclei stained by anti-VDR in the myometrial and leiomyoma tissue was 79.52 % (± 4.32) and 60.22 % (± 7.24), respectively (p < 0.0001)." (PMID 33952298, 2021). "Many of these studies showed that expression of VDR is lower in fibroids." (PMID 33807176, 2021). "We determined the expression of VDR in the uterine muscle of women without fibroids (control group)." (PMID 36014877, 2022). "Lower VDR expression in uterine muscle in the peripheries of fibroids compared to that in non-fibroid uterine muscle may be a potential cause of the development of new fibroids." (PMID 36014877, 2022). "Our VDR expression studies were performed immunohistochemically with tissue microarrays (TMA) in three tissue groups: 98 uterine myoma tissues, 98 uterine tissues (tumor margin), and 12 tissues of normal uterine muscle (i.e., without fibroids)." (PMID 36014877, 2022).